HIF1A (hypoxia inducible factor 1 subunit alpha)
Diseases named in the same sentence as HIF1A in open-access papers (continued):
Sharing a sentence is not in itself a finding about the gene and the disease.
Sepsis (continued). "Thus, we hypothesis that the timing of myeloid HIF-1α accumulation and activation has a significant impact on the transcription of the downstream mediators of the peripheral glycolytic response, as well as on cross-talk with other essential signaling systems during the acute response to sepsis." (PMID 30524296, 2018). "Furthermore, the current study showed that the rats with sepsis exhibited higher expressions of miR-31, HMOX1, NF-κB, and HIF-1α in addition to decreased expressions of IκB, ZO-1, and Occludin." (PMID 30340459, 2018). "Lastly, we did not evaluate the levels of VEGF-A and HIF-1α in another viral disease -especially the other hemorrhagic fevers- or patients with sepsis." (PMID 29026849, 2017). "We aimed to demonstrate whether HIF-1α and VEGF, related to sepsis and viral infection, were correlated with pathogenesis of CCHF disease." (PMID 29026849, 2017). "Genetic variants in HIF-1α and PHD2 genes exist in Caucasians but do not appear to alter 30-day mortality in sepsis." (PMID 27515179, 2016). "This indicated that XBP1 plays a crucial role in inflammation and injury in sepsis-associated AKI, although it is not directly associated with HIF-1α, its mediated inflammatory response may interact with HIF-1α signalling." (PMID 41602837, 2026). "However, there is currently a lack of comprehensive studies delineating the role of HIF-1α in sepsis and ARDS." (PMID 40887582, 2025). "In addition, during sepsis, the restriction of glycolysis led to neutrophil immunosuppression and may be regulated by LDHA downregulation mediated by the PI3K/Akt‐HIF‐1α pathway." (PMID 39611400, 2024). "Furthermore, research has demonstrated that in both sepsis-induced lung injury patients and corresponding mouse models, NETs trigger the METTL3-mediated m6A-IGF2BP2-dependent pathway, resulting in the upregulation of HIF-1α." (PMID 39712019, 2024). "It would thus be of great interest to investigate whether hepatic PPARα stimulation with pemafibrate or GW7647, well known PPARα agonists, in the absence of HIF1α in hepatocytes during sepsis might be able to restore PPARα functioning and reduce lipotoxicity." (PMID 37006237, 2023). "The aim of this study was to investigate the gene expression profile of HIF1A, ISG15, HK2, LDHA, HMOX1, EPO, and VEGFA under the setting of sepsis and septic shock, and furthermore to evaluate whether any of these molecules has potential value as a prognostic factor." (PMID 37367740, 2023). "Furthermore, the expression of HIF1α and its target genes were higher in non-survivors sepsis patients compared to survivors." (PMID 37006237, 2023). "Since a conditional knock-out of HIF1α or HIF2α in myeloid cells protects against LPS, it might be of interest to study whether KC specific knock-out mice for HIF1α and/or HIF2α are protected against LPS-induced endotoxemia and CLP polymicrobial sepsis." (PMID 37006237, 2023). "Furthermore, since HIFs are thought to be involved in increased glycolysis thereby contributing to the higher blood lactate levels during sepsis, and a clear crosstalk exists between GR and HIF, we investigated if HIF1α and/or HIF2α are involved in the GCR induced in the liver during sepsis." (PMID 37006237, 2023). "The boxplot revealed 26 differentially expressed genes between the sepsis-induced ALI and control samples: Ncf2, Slc2a6, Cd44, Txnip, Slc2a1, Ubc, Hspb1, Zfp36, Arntl, Ddit4, Tnfaip3, Txnrd1, Mt1, Hmox1, Gch1, Gclc, Stat3, Egfr, Hif1a, Bach1, Socs1, Dusp1, Cdkn1a, Fth1, Steap3, and Alox12." (PMID 37081490, 2023). "Altogether, we conclude that HIF proteins are not involved in the appearance of GCR in liver during sepsis and that HIF1α in hepatocytes of septic animals might be involved in the reduced PPARα signaling." (PMID 37006237, 2023).
Sepsis (continued). "Restoration of FoxM1 expression in ECs of these EC-specific Hif1a KO mice normalized endothelial proliferation and vascular repair, demonstrating that pulmonary vascular endothelial HIF-1α is required for lung endothelial regeneration and vascular repair via FoxM1 after sepsis-induced lung injury." (PMID 35563731, 2022). "Similarly, NBP might be an ideal approach for sepsis, IBD, RA, cancer, and autoimmune encephalomyelitis as its ability to target HIF-1α, AMPK/SIRT1, PI3K/Ak, and Nrf-2/HO-1." (PMID 35422893, 2022). "Overexpression of FoxM1 in the LECs of these EC-specific HIF-1α knockout mice normalized LEC proliferation and vascular repair, showing that LEC HIF-1α is required for LEC regeneration and vascular repair via FoxM1-mediated EC proliferation after sepsis-induced lung injury." (PMID 35053299, 2022). "Moreover, previous studies of sepsis and ALI have demonstrated that HIF-1α expression may induce acute lung epithelial damage and the production of numerous proinflammatory cytokines such as IL-6, MIP-2 and TNF-α via the nuclear factor-κB (NF-κB) pathway." (PMID 32353952, 2020). "Hence, in sepsis, STAT3 also mediated HIF-1α transcriptional activity in its signaling pathway." (PMID 32089644, 2020). "Many of these findings (increased oxidative stress, HIF-1α and bcl-2 expression after isoflurane exposure) are consistent with prior work on APC and may play a role in the organ protection observed by previous authors during sepsis." (PMID 31307382, 2019). "However, neither of the analyzed genetic variants of HIF-1α and PHD2 genes turned out to be independent risk factors for 30-day mortality of severe sepsis." (PMID 27515179, 2016). "Similarly, in our study, NAD+ consumption induced mitochondrial insufficiency elicited the stabilization of HIF‐1α, which in turn triggered the metabolic shift to aerobic glycolysis, thus CD38‐NAD+‐HIF‐1α axis was found to induce metabolic rewiring of monocytes in sepsis." (PMID 40145840, 2025). "Finally, divergently from HIF1α, plasma lactate levels may reflect pyruvate accumulation rather than cell hypoxia in sepsis and injury." (PMID 22781303, 2012). "Unfortunately, although we were able to detect HIF activity in the liver during sepsis, we were unable to observe a survival benefit in LPS-induced endotoxemia and CLP polymicrobial sepsis in mice lacking HIF1α and/or HIF2α in hepatocytes." (PMID 37006237, 2023). "Further HIF-1α expression (p = 0.046) was found to decrease in sepsis; however, HMGB1 was decreased but not significant in sepsis compared to w/o sepsis patients." (PMID 35681439, 2022). "Cit-AuNP treatment performed 2 h after sepsis induction did not change the AP1 and HIF-1α expressions in brain of mice as well." (PMID 33608025, 2021). "However, hepatocyte-specific knock-out mice for HIF1α and/or HIF2α did not yield any survival benefit against LPS-induced endotoxemia and CLP polymicrobial sepsis." (PMID 37006237, 2023). "Therefore, we wanted to investigate the involvement of hepatocyte-specific expression of HIF1α and/or HIF2α in the GCR observed during sepsis, however without any positive results." (PMID 37006237, 2023). "However, the effects of HIF-1α and LMWH on sepsis-related acute lung injury (ALI) have not been fully delineated." (PMID 32353952, 2020). "Therefore, we wanted to investigate whether HIF1α and HIF2α expression in hepatocytes contributes to the GCR and PPARα failure present in sepsis, as this has not been studied before." (PMID 37006237, 2023). "Therefore, we investigated whether the absence of HIF1α and/or HIF2α in hepatocytes has an influence on the hypoglycemia and increased FFA and KB levels during sepsis." (PMID 37006237, 2023). "However, HIF-1α and LMWH affect sepsis-related diaphragm injury has not been investigated." (PMID 33567713, 2021).
liver cancer (150 papers, 2012 to 2026). An epithelial or non-epithelial malignant neoplasm that arises from the liver. "Our bioinformatics analysis revealed that both TCF12 and HIF-1α are significantly overexpressed in liver cancer and are associated with poor prognosis." (PMID 40190273, 2025). "The expression of hypoxia-inducible factor-1α (HIF-1α) is reportedly upregulated in liver cancer tissues, which is directly linked to the resistance of 10-HCPT." (PMID 33427515, 2021). "SNP rs2057482 in HIF1A gene is significantly associated with clinical outcomes of Chinese liver cancer patients after surgery." (PMID 26872370, 2016). "The HIF1 α transcription factor has been linked in the context of the liver to lipid metabolism and vascular regulation during liver regeneration and to enhanced proliferation of liver cancer cell lines." (PMID 38216754, 2024). "SS NPs could induce apoptosis via mitochondrial apoptosis pathway, as well as glycolysis inhibition associate with the regulation of PI3K/AKT/HIF-1α signal path, which may offer an underlying therapeutic target for liver cancer." (PMID 34930288, 2021). "They reached the same conclusion that HIF-1α can promote the progression of liver cancer by affecting MMP2 and MMP9." (PMID 40563539, 2025). "Experimental studies on cell function have demonstrated that HIF-1α enhances the migration and tube-forming capabilities of liver cancer vascular ECs, as well as increases permeability between ECs." (PMID 40190273, 2025). "For example, in liver cancer, miR‐138‐5p inhibits vascular simulation in HepG2 and Hep3B cells by suppressing the HIF‐1α/VEGFA signalling pathway." (PMID 40735832, 2025). "Recent studies unravel that DKC1 promotes proliferation, survival, invasion or metastasis of colon and liver cancer cells by increasing HIF-1α expression and antioxidative effect, respectively." (PMID 40458122, 2025). "It is known that CCL5 promotes tumour metastasis by inhibiting the ubiquitin degradation of HIF1α in human liver cancer, and that CCL5 expression is increased in human oesophageal cancer." (PMID 40500939, 2025). "This study investigated the effects of TCF12 and HIF-1α on tube formation and drug sensitivity in liver cancer vascular ECs." (PMID 40190273, 2025). "This study aims to explore how the interaction between TCF12 and hypoxia-inducible factor 1-alpha (HIF-1α) affects vascularization and drug sensitivity in liver cancer." (PMID 40190273, 2025). "In liver cancer samples, unpaired tumor tissues exhibited significantly higher HIF-1α expression than adjacent normal tissues." (PMID 40190273, 2025). "TCF12 promotes angiogenesis by stabilizing HIF-1α and modulates tumor sensitivity to sorafenib, highlighting its potential as a therapeutic target in liver cancer." (PMID 40190273, 2025). "Database analyses reveal that HIF-1α is highly expressed in liver cancer and correlates with poor prognosis in patients." (PMID 40190273, 2025). "Clinical trials have shown a remarkable relationship between serum copper levels and HIF-1α levels in liver cancer patients, demonstrating that copper has a considerable role in HIF-1α activation and liver cancer progression." (PMID 38662225, 2024). "The miR-138-5p miRNA can suppress the vascular simulation of HepG2 and Hep3B cells via inhibition of the HIF-1α/VEGFA cascade in liver cancer." (PMID 39596660, 2024). "Liver cancer organoids displayed higher expression of the HIF-1A gene and protein compared to those grown in the 200 μM CoCl2-containing media for 14 days." (PMID 39567394, 2024). "In liver cancer, melittin reduces CoCl2-induced migration, invasion, and hypoxia-induced vasculogenic mimicry by decreasing HIF-1α and reversing EMT markers." (PMID 39519238, 2024).
liver cancer (continued). "The CRISPR liver cancer database was used to construct scatter plots showing that IDH1 protein expression was negatively correlated with the expression of HIF1a in HCC cells." (PMID 38622131, 2024). "In lipid metabolism, the HIF-1α inhibitor YC-1, in combination with palmitic acid and L-carnitine, activates fatty acid β-oxidation and induces ROS overproduction, promoting liver cancer cell apoptosis." (PMID 39434182, 2024). "In liver cancer, tumor cells promote the recruitment and expansion of MDSCs within the TIME by releasing hypoxia-inducible factor 1-alpha (HIF-1α) and tumor-associated cytokines, such as IL-6, IL-1β, GM-CSF, G-CSF, VEGF, MCP-1, and MIF." (PMID 39596288, 2024). "MIAT knockdown potentiated the therapeutic effect of TAE in liver cancer by regulating the miR-203a/HIF-1α axis in vitro and in vivo." (PMID 39204162, 2024). "Liver cancer organoids with higher expression of HIF-1A showed more enhanced glycolytic activity than organoids cultured in 200 μM CoCl2 for 14 days." (PMID 39567394, 2024). "In recent years, more and more natural products targeting HIF-1α and ROS expression and inhibiting liver cancer glycolysis have been studied for the treatment of liver cancer." (PMID 37663261, 2023). "Interfering with METTL3 expression can reduce the level of m6A modification of HIF1α and inhibit the metabolic reprogramming of colorectal and liver cancer cells." (PMID 36855123, 2023). "It suggests that autophagy can inhibit the proliferation of liver cancer cells through HIF‐1α signalling pathway." (PMID 37038623, 2023). "Collectively, these findings indicate that overexpression of HIF-1α can restore the proliferative capacity of liver cancer cells suppressed by RPLP2 depletion." (PMID 38052785, 2023). "AMPK, inflammation-related β-catenin, COX-2, HMGB1, hypoxia-related HIF-1α, and cellular senescence-related p16 are all important in the development of liver cancer." (PMID 36937390, 2023). "Curcumin also reduced the expression of HIF-1α, inhibited glucose consumption and lactic acid production, alleviating the drug resistance of liver cancer cells to chemotherapy." (PMID 37663261, 2023). "PFKFB3, the key factor in the Warburg effect, was overexpressed in liver cancer, and the regulation of IL-6/HIF-1α/PFKFB3 played an important role in dosage-specific pro-invasive effect of sorafenib." (PMID 37476196, 2023). "Transcriptionally, the hypoxia-induced HIF1α/2α signaling pathway can negatively regulate YTHDF2 expression to favor tumor growth in liver cancer." (PMID 37012388, 2023). "Recent research suggests that LY-294002 is a potent and selective PI3K inhibitor that increases the chemosensitivity of liver cancer to oxaliplatin by blocking the PI3K/AKT/HIF-1α pathway." (PMID 38283752, 2023). "expanded on this intricate relationship, suggesting a mechanism where interferon-a inhibits HIF1a signaling in liver cancer cells by suppressing FosB transcription." (PMID 37817774, 2023). "PB2 inhibited the expression and nuclear translocation of PKM2, thereby disrupting the interaction between PKM2/HSP90/HIF-1α, and inhibiting the aerobic glycolysis and proliferation of liver cancer cells." (PMID 37663261, 2023). "Further regression analysis using cBioPortal revealed that S100B mRNA level was positively correlated with HIF-1α expression in liver cancer." (PMID 35368338, 2022). "Intriguingly, the protein level of Kcr was positively correlated with HIF1α in the cohort of patients with liver cancer derived from a tissue microarray (patients with liver cancer n = 32, Spearman correlation r = 0.578, P < 0.001)." (PMID 35977926, 2022). "In the TCGA liver cancer cohort, we did observe that liver cancer patients with high expression of HIF1A or NRF2 (NFE2L2) tend to have a worse prognosis (p-value < 0.1)." (PMID 35912211, 2022). "KDM4A-AS1 is considered to be a new hypoxia response gene that promotes the growth and metastasis of hepatic cancer through KDM4A-AS1/KPNA2/HIF-1α signaling." (PMID 36159561, 2022).
liver cancer (continued). "The WB analysis demonstrated significant up-regulation of HIF-1α in various liver cancer cell lines under hypoxia." (PMID 36335129, 2022). "The high expression of HIF-1α in liver cancer tissues is related to 10-HCPT resistance, which is considered a potential cancer target for natural products." (PMID 35153781, 2022). "Overexpression of circ_EPHB4, exhibiting low levels in liver cancer cells, suppressed the migration by downregulating HIF1A." (PMID 36230902, 2022). "Recently, some studies focused on CK‐mediated inhibition of the proliferation of human liver cancer cells by regulating HIF‐1α‐mediated glycolysis." (PMID 34793617, 2022). "In the current study, we identified hypoxia as a potential inducer to promote crotonylation in liver cancer because the crotonylation level is tightly regulated by hypoxia and positively related to the expression of HIF1a." (PMID 35977926, 2022). "In liver cancer, HIF-1α promotes LOXL2 expression, which promotes EET and VM through the Snail/FBP1/VEGF pathway." (PMID 33397409, 2021). "First, tumor cell apoptosis and proliferation are promoted in hypoxic environments, and hypoxia-inducible factor 1α (HIF1α) is a significant hypoxia-inducing factor that is related to the movement and adhesion of liver cancer tumor cells in such environments." (PMID 33505467, 2021). "In this study, we have investigated the anti-angiogenic and pro-apoptotic potential of taxifolin against liver cancer and the subsequent effects of taxifolin dose on Hif1-α,VEGF and Akt expression." (PMID 34113483, 2021). "Hypoxia-inducible factor-1a (HIF-1α) enhances liver cancer progression by inducing M2 polarization and suppressing M1 polarization in macrophages." (PMID 34716294, 2021). "As Hif1-α is mechanistically involved in the development and progression of liver cancer, so pharmacological modifiers of Hif1-α in liver cancer treatment have been proposed in many studies (Ju, Colgan & Eltzschig, 2016)." (PMID 34113483, 2021). "Recent studies have shown that Huaier can inhibit liver cancer by downregulating the expression of HIF-1α and VEGF." (PMID 32596377, 2020). "For example, ZFHX3 promotes liver cancer cells’ tumor growth by interacting with HIF1A to enhance angiogenesis." (PMID 33217982, 2020). "After treatment with CK, we found that the expression of PHD increased in liver cancer cells exposed to hypoxic conditions, with a corresponding increase in the level of hydroxylation of HIF-1α." (PMID 33363466, 2020). "IGFBP-1, which is expressed in the liver and binds IGF-1, is regulated by HIF1α in HepsG2, a human liver cancer cell line." (PMID 32610471, 2020). "This suggests that CK inhibits the expression of Bclaf1 and the binding of Bclaf1 to HIF-1α in hypoxic liver cancer cells." (PMID 33363466, 2020). "In liver cancer, miR-3662 can inhibit the growth and proliferation of liver cancer cells by negatively regulating HIF-1α-mediated glycolysis." (PMID 33109235, 2020). "In order to further clarify the interaction mechanism between Bclaf1 and HIF-1α, we use CRISPR/Cas9 technology to knock out Bclaf1, and detect the expression of HIF-1α in liver cancer cells after knocking out Bclaf1 under hypoxia." (PMID 33363466, 2020). "Increased Bclaf1 and HIF-1α expression promoted the ubiquitination of HIF-1α and inhibited the glycolysis pathway, thereby inhibiting the proliferation of liver cancer cells." (PMID 33363466, 2020). "They find that oleic-acid treatment activates the FABP5/HIF-1α axis, promoting lipid accumulation and cell proliferation in liver cancer cells." (PMID 33128030, 2020). "In our study, we delivered the HIF-1α shRNA into the liver cancer cells, to inhibit blood vessels and the growth of the tumor." (PMID 30911540, 2019).